OR4E1 (olfactory receptor family 4 subfamily E member 1)
Description:
Odorant receptor.
Synonyms: OR4E1P
Tractability: Antibody: UniProt places it where antibodies can reach, with medium confidence; UniProt predicts a signal peptide or a membrane-spanning region; its Gene Ontology location is reachable by antibodies, with medium confidence.
Gene: Protein-coding gene on chromosome 14 (21,667,886 to 21,673,818, reverse strand). Ensembl gene ENSG00000276240.
Subcellular location: Cell membrane
Pathways (Reactome):
Sensory Perception: Expression and translocation of olfactory receptors
Gene Ontology:
Molecular function: odorant binding; olfactory receptor activity; G protein-coupled receptor activity
Biological process: detection of chemical stimulus involved in sensory perception of smell; G protein-coupled receptor signaling pathway
Cellular component: membrane; plasma membrane
Homologues: Orthologues: macaque OR4E1 (97% identical), chimpanzee OR4E1 (94% identical), rabbit OR4E1 (89% identical), dog OR4E1 (87% identical), rat Or4e1 (87% identical), mouse Or4e1 (87% identical), pig OR4E1 (86% identical), rat Or4e5 (81% identical), mouse Or4e5 (80% identical). Paralogues in human: OR4E2 (62% identical), OR4Q3 (52% identical), OR4C11 (50% identical), OR4K14 (50% identical), OR4S1 (50% identical), OR4S2 (50% identical), OR4K15 (49% identical), OR4X1 (49% identical), OR4A15 (49% identical), OR4A47 (48% identical), OR4D5 (48% identical), OR4N5 (48% identical), and 116 more.
Diseases named in the same sentence as OR4E1 in open-access papers:
OR4E1 is named in the same sentence as 1 disease in open-access papers, as found by Europe PMC text mining. Sharing a sentence is not in itself a finding about the gene and the disease. The quoted sentences say what the papers report.
pulmonary diseases (1 paper, 2020). "The other three genetic loci were rs188904275 in JAKMIP2 (p-value = 3.7×10−8), rs184670665 near IMPG1 (p-value = 2.4×10−10), and rs73586669 near OR4E1 (p-value = 2.4×10−8), with JAKMIP2 previously found to be associated with Body Mass Index (BMI) measurements and pulmonary diseases." (PMID 33075057, 2020).